ENSG00000268797 (novel protein)
Gene: Protein-coding gene on chromosome 19 (40,801,297 to 40,898,282, forward strand). Ensembl gene ENSG00000268797.
Genetic constraint (gnomAD): Missense variants: 57 observed, 58.33 expected, observed/expected ratio (o/e) 0.98, 90% interval 0.79 to 1.22. Synonymous variants: 31 observed, 23.21 expected, observed/expected ratio (o/e) 1.34, 90% interval 1 to 1.78.